TNF (tumor necrosis factor)
Diseases named in the same sentence as TNF in open-access papers (continued):
Sharing a sentence is not in itself a finding about the gene and the disease.
colitis (continued). "Similarly, indole-3-carbinol (an indole resulting from the hydrolysis of glucobrassicin) was able to significantly decrease the intestinal expression of NF-κB and several inflammatory factors such as TNF-α, IL-1β, IL-6, and IL-8 in mice with colitis." (PMID 40508374, 2025). "Similarly, L15 exerts anti-inflammatory effects in colitis by suppressing LPS-induced NF-κB activation and lowering IL-6 and TNF-α levels." (PMID 41141596, 2025). "Data revealed that Anakinra can alleviate experimental colitis in Winnie-TNF-KO mice." (PMID 40642091, 2025). "In addition, TNF-α and IL-1β levels were lower in betanin-supplemented rats compared to other colitis-affected rats." (PMID 41515203, 2025). "We observed increased levels of pro-inflammatory factors (IL-1β, TNF-α, and IL-17) in the colon tissues of KOIEC mice compared to those in WT mice during DSS-induced colitis, via the enzyme-linked immunosorbent assay (ELISA) and quantitative real-time PCR (qPCR)." (PMID 40089459, 2025). "These anti-inflammatory and antioxidant effects have been similarly reported in various pathological models, including colitis, ischemia–reperfusion injury, and diabetes, where MB administration reduced TNF-α, IL-1β, IL-6, and CRP levels, suppressed MPO and MDA, and enhanced SOD activity." (PMID 40870501, 2025). "Many studies have shown that CB or AKK can play a protective role in mouse colitis by regulating some key components related to the inflammatory response, such as pro-inflammatory cytokines (IL-1β, IL-6, and TNF-α) and anti-inflammatory cytokines (IL-4 and IL-10)." (PMID 39840995, 2025). "More importantly, combining anti‐TNF‐α therapy with crotonate supplementation could effectively alleviate colitis." (PMID 40650658, 2025). "Moreover, studies using anti-TNF-α and anti-IL-6 monoclonal antibodies have demonstrated that reducing TNF-α and IL-6 levels significantly alleviates colonic damage in colitis." (PMID 41227760, 2025). "In mice with DSS-induced colitis, levels of the pro-inflammatory cytokines TNF-α, IL-1β, and IL-6 were significantly elevated, whilst the anti-inflammatory cytokine IL-10 was markedly decreased, indicating an intense inflammatory response and immune dysregulation." (PMID 40777179, 2025). "Additionally, the UAF1 inhibitor demonstrated a significant suppression of the levels of inflammatory markers (TNF-α, IL-6, IL-17, and IL-1β) in the colon tissue of colitis mice (P < 0.05 and P < 0.01)." (PMID 39966502, 2025). "Accordingly, PAG resin (400 mg/kg) + honey (400 mg/kg) caused significant inhibition of the inflammation of the bowel and colonic ulcer incidence in acetic acid‐induced colitis in rats, which were represented by reduced serum inflammatory mediators (IL‐6 and TNF‐α cytokines)." (PMID 40034223, 2025). "Moreover, these molecules have been demonstrated to inhibit the infiltration of TCD3+ cells and CD68+ macrophages in the intestinal mucosa, thereby alleviating colitis by reducing the production of pro-inflammatory cytokines TNF-α and IL6 by macrophages." (PMID 40130239, 2025). "In this study, we investigated whether L. murinus, a putative probiotic strain, can influence AHR signaling and mitigate TNF-α-induced epithelial dysfunction in an in vitro colitis model." (PMID 41373818, 2025). "Rutin can decrease TNF-α levels in experimental animals induced with colitis." (PMID 40395731, 2025). "Additionally, certain E. faecalis strains have been reported to reduce expression of pro-inflammatory cytokines such as TNF-α and IL-6, which drive neutrophil-mediated inflammation in colitis models." (PMID 41472066, 2025). "Importantly, mice with a knockout of USP16 display a reduction in colitis severity, characterized by decreased levels of pro-inflammatory cytokines such as TNF, IL-12, and IL-23." (PMID 40822862, 2025).
colitis (continued). "Moreover, ELISA analyses demonstrated that quercetin alleviated colonic inflammation by significantly decreased the levels of IL-1β, IL-6, and TNF-α by 23.2 %, 19.9 %, and 20.7 %, respectively, in colitis mice." (PMID 40909112, 2025). "However, the excessive TNF produced at the onset of colitis inhibits bile acid detoxification in intestinal epithelial cells, leading to bile acid overload and consequently apoptosis." (PMID 41515203, 2025). "Conversely, suppression of NPY expression through the administration of antisense oligodeoxynucleotides (ODNs) in rats with DSS-induced colitis not only limits leukocyte infiltration but also diminishes TNF-α production, thereby mitigating intestinal inflammation." (PMID 41007974, 2025). "These symbionts were exclusively enriched in the control group in our study, where they exhibited strong negative correlations with pro-inflammatory cytokines (IL-6, TNF-α) and inflammation-related genes (Lcn2, Mmp3), suggesting their protective role in mitigating colitis severity." (PMID 40356657, 2025). "Nowadays, 5-aminosalicylic acid, systemic corticosteroids, antibiotics (e.g. metronidazole, ciprofloxacin, and vancomycin), immunomodulators (azathioprine, 6- mercaptopurine, methotrexate, and cyclosporine), and infliximab, a TNF antagonist, are commonly used to treat of colitis." (PMID 40656621, 2025). "In addition, these probiotics significantly inhibited blood lipopolysaccharide and TNF-α levels in mice with TNBS induced colitis." (PMID 39346650, 2024). "TNF-α, IL-6, and IL-1β are highly expressed in experimental mice colitis." (PMID 39148547, 2024). "Additionally, they created a predictive tool using a five-mRNA biomarker panel to forecast anti-TNF mAb response in colitis patients for potential clinical use." (PMID 39062093, 2024). "The compound 1,8-cineole demonstrated the downregulation of inflammatory responses in dextran sulfate sodium (DSS)-induced colitis in mice and decreased proinflammatory chemokine production in TNF-stimulated HT-29 cells, proving to be a potent compound in treating human IBD." (PMID 39065669, 2024). "Similarly, Chen and colleagues found that L. acidophilus reduced TNF-α expression in the colons of mice exposed to colitis." (PMID 39323474, 2024). "In conjunction with an abundance of effector T cell responses, myeloid cells in ICI-colitis also display an inflammatory gene signature enriched in TNF-α- and IFNγ-inducible elements such as CXCL16, CXCL9 and CXCL10, which encode chemokines that attract CXCR6+ and CXCR3+ T cells, respectively." (PMID 39247203, 2024). "Furthermore, treatment with 10, 25, and 50 mg/kg of syringic acid significantly decreased the tissue levels of TNF-α and IL-1β proteins compared to the UC group in rats with acetic acid-induced colitis." (PMID 38732594, 2024). "Similarly, the oral administration of Butyricicoccus B pullicaecorum has shown a significant protective effect in reducing intestinal myeloperoxidase, tumor necrosis factor α, and interleukin-12 levels in colitis." (PMID 39457690, 2024). "Spirulina platensis (SP) and Dunaliella salina (DS) were investigated on acetic acid-induced colon inflammation in rats, and both microalgae demonstrated anti-inflammatory properties by inhibiting the production of proinflammatory cytokines such as IL-1β, TNF-α, and IL-6." (PMID 39195452, 2024). "Additionally, experimental murine colitis models demonstrated that neutralizing antibodies against TNF-α, IL-12, or IL-18 prevent the onset of colitis which further indicate that proinflammatory immune responses predominate in inflamed mucosa." (PMID 39234241, 2024). "The plasma levels of MCP and TNF-α were significantly higher in obese TNBS colitis treadmill-exercising mice when compared to corresponding SD-fed animals and the administration of IAP significantly decreased the concentration of these cytokines in obese mice (p < 0.05)." (PMID 38255781, 2024).
colitis (continued). "Additionally, at a dose of 40 mg/kg, sinapic acid demonstrated a significant decline in mean TNF-α and IL-6 levels in mice with acetic acid-induced colitis." (PMID 38732594, 2024). "Clarithromycin inhibits LPS-induced NF-κB (p65) DNA binding in vivo, alleviates DSS-induced colitis in murine models, and suppresses TNF-induced NF-κB (p65) nuclear localization in human ileal organoids, further study is necessary to confirm its effects in patients." (PMID 39569001, 2024). "Mice with DSS-induced colitis exhibited significantly elevated levels of IL-6, TNF-α, and IL-1β." (PMID 39296302, 2024). "Notably, GM-CSF strongly promotes the differentiation of eosinophils from GMPs, along with their production of IL-6, TNF, and peroxidase, thereby exacerbating colitis." (PMID 39379604, 2024). "Indeed, the abundance of Dorea, associated with colitis, was found to negatively correlate with the production of SCFA and showed a strong positive correlation with TNF-α, a pro-inflammatory cytokine." (PMID 38369490, 2024). "Also, DHNA reduced DSS-induced colitis markers, such as inflammatory histological scores and TNFα expression, which again was inhibited by CH-223191." (PMID 39517263, 2024). "The levels of interleukin-6 (IL-6) and tumor necrosis factor-α (TNF-α) in the serum were measured to investigate the ability of the selected CFSs to reduce the level of pro-inflammatory cytokines in mice with DSS-induced colitis." (PMID 38674829, 2024). "In our study, we found that the lactate/GPR81 axis could limit experimental colitis by inhibiting TNF-α/NF-κB/MMP9 signaling." (PMID 38474712, 2024). "Furthermore, LM-CsA NPs significantly decreased the expression of inflammatory factors such as TNF-α and IL-6 and increased the expression of gut barrier-related proteins such as E-cadherin, ZO-1, and occludin protein in colitis mice." (PMID 39512421, 2024). "For example, the adoptive transfer of CD69-deficient CD4+ T cells into RAG-/- mice (deficient in lymphocytes) induced severe colitis due to the increased secretion of proinflammatory cytokines (IFN-γ, TNF-α, IL-21) and decreased levels of anti-inflammatory cytokines (TGF-β1)." (PMID 39451246, 2024). "Accumulating evidence has revealed that AhR can mitigate colitis by decreasing the serum inflammatory cytokines/chemokines (e.g., TNF‐α, IFN‐γ, MCP‐1, and IL‐17), enhancing the expression of IL‐10 and IL‐22, and strengthening the intestinal epithelial cell barrier." (PMID 38882491, 2024). "TNF-α is a key mediator of the acute inflammatory response, is chemotactic for neutrophils and macrophages, and plays an important role in the pathogenesis of UC and in experimentally induced colitis following DSS administration." (PMID 39597805, 2024). "Similarly, oral administration of another AhR agonist, β-naphthoflavone, was shown to decrease the severity of DSS-induced colitis while reducing pro-inflammatory cytokines such as tumor necrosis factor -α (TNF-α), IL-6, and IL-1β." (PMID 39767818, 2024). "The reduced severity of colitis in MC-170073-treated mice given DSS was also associated with lower levels of both colonic MPO and the proinflammatory cytokines IL-1β, IL-6, and TNF-α." (PMID 38713616, 2024). "Other studies have reported that hyperalgesia owing to central sensitization via TRAF6/nuclear factor-κB (NF-κB) was observed in visceral pain models, as knockdown of TRAF6 suppressed colitis-induced activation of NF-κB and increased TNF-α and IL-1β in the spinal cord." (PMID 39044893, 2024). "In cases of moderate-to-severe colon inflammation, other drug classes, such as corticosteroids like prednisolone and anti-TNF-α antibodies, may also be utilized." (PMID 38255916, 2024). "Moreover, YOD1 deficiency did not change cytokine production and signal transduction in macrophages upon stimulation with TNF, a detrimental cytokine in colitis." (PMID 39333628, 2024). "Many studies have shown that cytokines IL-6, IL-1β, and TNF-α play an important role in colitis." (PMID 38398846, 2024).
colitis (continued). "Furthermore, IAA-treated colitis mice exhibited lower levels of pro-inflammatory cytokines including IL-1β and TNFα than the colitis mice." (PMID 39068517, 2024). "Finally, it is revealed that macrophage iron overload impairs the therapeutic effectiveness of anti‐TNF‐α antibodies in colitis, which can be reversed by butyrate supplementation." (PMID 38235606, 2024). "Compared with the model group, different concentrations of oat and bran treatment groups could promote the expression of IL-10 and inhibit the gene expression of IL-6 and TNF-α, thus mitigating the mucosal damage caused by DSS-induced colitis." (PMID 39770986, 2024). "In addition, previous studies have shown that Lactobacillus can inhibit the expression of TNF-α and IL-1β in macrophages, thereby alleviates colitis." (PMID 39346650, 2024). "Furthermore, eFMT also increased TNF-α and IL-1β expression and NF-κB+CD11c+ cell population in the colon, resulting in colitis." (PMID 38885258, 2024). "In DSS-induced colitis, specifically, immunocyte dysfunction leads to abnormal secretion levels of pro-inflammatory cytokines such as tumor necrosis factor-alpha, interleukin-1β, and IL-6, while anti-inflammatory cytokines like IL-10 secretion decrease (p < 0.01)." (PMID 38612465, 2024). "Moreover, D. vulgaris also significantly augmented DSS-induced colitis by exacerbating the damage of gut barrier and the secretion of inflammatory cytokines, for instance, IL-1β, iNOS, and TNF-α." (PMID 39060944, 2024). "Indeed, prophylactic TNFα blockade has been shown to uncouple efficacy from colitis-like toxicities during checkpoint inhibitor treatments of xenografted mice." (PMID 38114742, 2024). "Notably, its therapeutic potential is synergistic with existing TNF-α inhibitor infliximab in colitis treatment." (PMID 38997284, 2024). "In addition, intraperitoneal injection of NOS inhibitors reduced the concentrations of TNF and NO in the hippocampus, reversing the anxiety- and depression-like behaviors, although this seemed to have little effect on the improvement of colitis." (PMID 38576620, 2024). "Additionally, hydroxytyrosol has been shown to lower levels of IL-1β, IL-6, and TNF-α and increase the level of the anti-inflammatory cytokine IL-10 to ameliorate intestinal inflammation in mice colitis models." (PMID 38891778, 2024). "Furthermore, Tlr7-/- and Atg16l1ΔCd11c mice were more susceptible to dextran sulfate sodium colitis with an increase in disease activity index, histoscore, and increased secretion of IFN-γ and TNF-α." (PMID 39464882, 2024). "The results revealed significant IL‐1β, IL‐6, and TNF‐α pro‐inflammatory cytokine up‐regulation in the UC model group (p < 0.05), suggesting the presence of an inflammatory response in the mice with colitis." (PMID 38334213, 2024). "Suppress colitis-stimulated tissue oxidative stress.Suppress TNF-α, IL-6, IL-1β, and IL-33." (PMID 38585461, 2024). "Similarly, previous research has also found that PA can effectively inhibit the elevation of IL-1β, IL-6, and TNF-α levels in colitis." (PMID 39064674, 2024). "This study showed that both OBB and BBR can increase the abundance of Bacteroides, and OBB has superior anti-colitis activities, including improving the intestinal mucosal barrier, inhibiting colitis tissue damage, and reducing pro-inflammatory factors such as IL-6, IL-1β, IL-17, TNF-α and IFN-γ." (PMID 38660314, 2024). "The key cytokines involved in colitis, such as TNF-α, IL-17A, and IL-1α, were used to test whether DSS-induced downstream cytokines restricted NEDD4L expression." (PMID 39688910, 2024). "The combination of TNF-α inhibitors and vitamin D in colitis remains to be elucidated." (PMID 39055880, 2024). "Several of the significantly co-occurring LR pairs were previously implicated in colitis, and are mostly involved in epithelial integrity and repair (DDR1-CDH1, DSG2-DSC2), immune recruitment (MIF-CD74), and TNF signaling (GRN-TNFRSF1A)." (PMID 38225383, 2024).
colitis (continued). "Indeed, additional deletion of Rip3 eliminated the spontaneous ileitis and colitis and rescued the death of Casp8fl/flVillinCre mice under LT + TNF challenge." (PMID 37855658, 2024). "Increased TNF-α secretion observed in Tlr7-/-, Atg16l1Cd11cCre, and Atg16l1Lyz2 mice may contribute to the susceptibility to DSS-induced colitis via its detrimental effects on intestinal epithelial cells." (PMID 39464882, 2024). "Based on emerging data that TNF inhibitors may allow effective management of ICB-related diarrhea/colitis, the study protocol recommended treatment with infliximab even for first-line treatment for a low-grade immune-mediated TRAE of diarrhea/colitis." (PMID 38871975, 2024). "KEGG analysis suggested that pathways like apoptosis, TNF, nucleotide oligomerization domain‐like receptor, IL‐17, and NF‐kappa B signaling pathways might be crucial in regulating colitis." (PMID 38372468, 2024). "The use of TNF antagonists is an important advance in the treatment of colitis." (PMID 39554349, 2024). "As a result of abrogated Th1 responses, STAT4-deficient mice are resistant to the development of Th1-mediated autoimmune diseases, including EAE, RA, colitis, myocarditis, and diabetes, because they produce a smaller amount of pro-inflammatory cytokines, such as tumor necrosis factor-alpha (TNF-α)." (PMID 38673659, 2024). "We also examined its effect on the intricate network of cytokines, chemokines, and transcription factors involved in chronic inflammation and colitis, including TNF-α, IL-6, IFN-γ, IL-1β, C-X-C motif chemokine receptor 3 (CXCR3), signal transducer and activator of transcription (STAT3), NF-κB." (PMID 39255739, 2024). "To gain a deeper understanding of the mechanism by which TP2 alleviates colitis, we utilized ELISA technology to assess typical pro-inflammatory and anti-inflammatory cytokines in rats’ colonic tissues, including TNF-α, IFN-γ, IL-1β, IL-6, IL-10, IL-17A, IL-22, and IL-23." (PMID 39776580, 2024). "The novel RORγt inverse agonist and TGR5 agonist compound 7 (University of Naples) has been shown to provide robust anti-inflammatory activity in mice models of TNBS-induced colitis, reducing TNFα, IL-1β, and IL-6 expression while increasing IL-10 and TGFβ expression." (PMID 38664391, 2024). "In addition, upregulated TNF-α in colitis leads to massive apoptosis and shedding of epithelial cells, thus altering intestinal permeability and ultimately aggravating inflammation." (PMID 38203732, 2024). "Additionally, in the DSS‐induced murine colitis model, we compared the effects of BsNb‐Fc with anti‐mouse TNF‐α mAb." (PMID 38533646, 2024). "Additionally, at doses of 20 and 40 mg/kg, ferulic acid ameliorated TNBS-induced colitis by inhibiting the production of proinflammatory cytokines (TNF-α, IL-1β, IL-6, AND IL-10) and downregulating COX-2 synthesis." (PMID 38732594, 2024). "In another study that utilized a DSS-induced mouse model of colitis, we found that APS could regulate the expression of inflammatory cytokines, including IL-2, IL-6, IL-12p70, IL-23 and TNF-α, in the colonic tissues of mice with colitis." (PMID 38202824, 2024). "The results showed ZW3 partially mitigated body weight loss, disease activity index (DAI), colon shortening, and suppressed immune response in colitis mice, as evidenced by the reduction in the levels of the inflammatory markers IL-1β, TNF-α, and IL-6 (p < 0.05)." (PMID 38203732, 2024). "Moreover, P. candolleana decreased the expression of IKBKB, JUN, CHUK, and TNF-α proteins, thus exerting anti-inflammatory and therapeutic effects on colitis." (PMID 38645561, 2024). "Inhibiting TNBS-induced colitis model in mice by reducing the secretion of cytokines related to Th1/Th17 immune responses and TNF in the intestine.Acting as a potential new molecule for the treatment of arthritis considering its therapeutic potential in collagen-induced arthritis." (PMID 39314046, 2024).